U6 (U6 spliceosomal RNA )
Synonyms: LOC124900883
Gene: Small nuclear RNA gene on chromosome 4 (135,315,418 to 135,315,522, reverse strand). Ensembl gene ENSG00000283432.
Gene Ontology:
Molecular function: U4 snRNA binding
Biological process: formation of quadruple SL/U4/U5/U6 snRNP; spliceosomal tri-snRNP complex assembly
Cellular component: U4/U6 x U5 tri-snRNP complex; U6 snRNP
Homologues: Orthologues: chimpanzee U6 (98% identical), macaque U6 (94% identical), mouse Gm25525 (84% identical), dog U6 (69% identical). Paralogues in human: RNU6-1316P (85% identical), RNU6-338P (85% identical), RNU6-38P (85% identical), RNU6-698P (85% identical), RNU6-86P (85% identical), RNU6-1124P (84% identical), RNU6-560P (84% identical), RNU6-664P (84% identical), RNU6-774P (84% identical), RNU6-891P (84% identical), RNU6-1145P (83% identical), RNU6-11P (83% identical), and 1288 more.